MALAT1 (metastasis associated lung adenocarcinoma transcript 1)
Diseases named in the same sentence as MALAT1 in open-access papers (continued):
Sharing a sentence is not in itself a finding about the gene and the disease.
cancer (continued). "An lncRNA termed MALAT1 contains about 8,000 nucleotides and was considered to be disorderly expressed in the growth, invasion, migration, as well as apoptosis of a wide range of different cancer cells, including lung cancer cells, gastric cancer cells, as well as liver cancer cells." (PMID 34599867, 2021). "More comprehensive studies with multiple independent cohorts of human cancer tissues of various organ origins, in vitro and in vivo function, and mechanism studies with rescue experiments are required to confirm the oncogenic or tumor suppressive role of MALAT1 in other cancers." (PMID 32174966, 2020). "In addition, by means of ChIP-PCR and RIP-PCR analysis, we also reveal that STAT3 may accelerate EMT progression and cancer metastasis through interaction with the MALAT1/miR-30a axis." (PMID 33123473, 2020). "Although lncRNA MALAT-1 does not encode a protein, it affects tumor proliferation, apoptosis, drug resistance, invasion, metastasis, and the process of the epithelial-mesenchymal transition, leading to a poor prognosis in patients with malignant tumors." (PMID 33052949, 2020). "Interestingly, the cancer-related MALAT1 was one of the most upregulated lncRNA." (PMID 32079166, 2020). "Furthermore, the expression of MALAT1 at different cancer stages was investigated." (PMID 31792655, 2020). "The biological behavior of MALAT-1 in cancer may explain this correlation." (PMID 32700729, 2020). "The lncRNA, Malat1, controls the expression of genes involved in nuclear processes and synaptogenesis, while the expression of the lncRNA PCAT-1 causes a homologous recombination deficiency and the suppression of the tumor suppressor BRCA2, which has been linked to cancer." (PMID 32922377, 2020). "As the increased level of MALAT1 expression might be an important feature of amoeboid cells, we further focused on analyzing the possible role of MALAT1 in the induction of the amoeboid phenotype in cancer cells." (PMID 32369931, 2020). "MALAT1 ASOs could also inhibit the metastasis of cancer cells and the tumor burden in mice." (PMID 31174564, 2019). "Thus, MALAT1 may be a potential therapeutic target, and MALAT1 ASOs may be a promising therapy approach for several types of cancer, but further assessment will be needed." (PMID 31448238, 2019). "In addition, MALAT-1 is a biomarker in various cancers including HCC." (PMID 31824761, 2019). "Thus, we propose an m6A switch that may explain one mechanism by which MALAT1 plays a role in cancer and m6A5044 as a potential biomarker for cancer." (PMID 31717552, 2019). "The capacity for Malat1 to drive proliferation and metastasis in pediatric solid tumors suggests that dysregulation of any of these regulatory components can be sufficient for the development of cancer and highlights the value of further research into the relatively new field of lncRNAs." (PMID 31616462, 2019). "Therefore, we speculated that MALAT1 could impact cancer progression and metastasis by regulating activity of immune checkpoint genes." (PMID 29416769, 2018). "In addition, all these studies concerning miR-9 and MALAT-1 expressions were performed on various cancer cell lines or primary tumors obtained from patients with stage I–III NSCLC, including adenocarcinoma, squamous cell carcinoma, or other large cell carcinoma." (PMID 30012957, 2018). "MALAT1 might play a pivotal role in the tumorigenesis of multiple types of cancers." (PMID 30093838, 2018). "Hence, emerging studies have implied that MALAT1 could serve as a potential prognostic biomarker for cancer patients on the basis of the complicated mechanisms of MALAT1 among multiple types of cancer." (PMID 30093838, 2018). "Besides, MALAT1 might influence carcinogenesis of cancers by activating Wnt/β-catenin, ERK/MAPK and PI3K/AKT pathways, which simultaneous activation of the oncogenic pathways might bring out highly carcinogenic effects." (PMID 30093838, 2018).
cancer (continued). "Notably, recent clinical studies have highlighted that MALAT-1 could be rated as a promising biomarker to aid in cancer diagnosis and prognosis." (PMID 29254244, 2017). "Given the oncogenic role of MALAT1 in human cancers, MALAT1 could mediate HUVECs proliferation in human carcinogenesis and cancer progression; thus, targeting of the MALAT1-miR-320a-FOXM1 signaling could serve as a novel strategy for therapeutic intervention in HUVECs-driven angiogenesis." (PMID 28977880, 2017). "MALAT-1 is a kind of non-protein-coding RNA transcripts, and its elevated expression status has been demonstrated to be implicated in the occurrence and development of various carcinomas." (PMID 29254244, 2017). "MALAT1 could promote tumor progression through multiple mechanisms in various types of cancer." (PMID 27486823, 2016). "MALAT1 may also serve as an independent prognostic biomarker for survival of these cancers." (PMID 27458156, 2016). "Jiao and colleagues found that MALAT-1 was over-expressed in cancer stem cells and could increase the percentage of PC stem cells through maintaining the self-renewing capacity, increasing resistance to anticancer drugs and promoting tumor angiogenesis in PC cell lines." (PMID 27429196, 2016). "Interestingly, a recent meta-analysis reported that MALAT1 overexpression was correlated with a poor overall survival and the pooled hazard ratio (HR) and corresponding 95% confidence interval (CI) was 1.94 (95% CI 1.59–2.38) in 792 cancer patients." (PMID 26522444, 2015). "In conclusion, MALAT1 may be a prognostic factor for patients with various types of cancer." (PMID 26420912, 2015). "Thus, we believe MALAT1 is a potential prognostic factor in human cancers including OSCC." (PMID 26522444, 2015). "Besides a putative role in alternative splicing, MALAT1 may also contribute to cancer metastasis through other mechanisms." (PMID 24346158, 2014). "Furthermore, MALAT-1 knockout mice do not show any detectable developmental or lethality phenotype when kept under normal stress-free conditions: MALAT-1 might thus be dispensable for normal development but highly important for cancer onset and progression." (PMID 25428918, 2014). "While not all MALAT1 isoforms encode mascRNA, the emergence of two oncogenic molecules from a single lncRNA gene during a single activity of DNA transcription raises intriguing questions about the mechanisms underlying the generation of specific isoforms, especially in the context of cancer." (PMID 40521240, 2025). "Quercetin inhibited cancer cell development and tumor growth, suppressed the EMT process, and promoted apoptosis through the downregulation of MALAT1 expression." (PMID 39825964, 2025). "A detailed investigation of their involvement in processes related to B cells and CD4+ T cells revealed that dendritic cells and macrophages were consistently correlated with MALAT1, FENDRR, FUS, and CRNDE across multiple cancers." (PMID 40728857, 2025). "These lncRNAs, which include MALAT1, H19, HOTAIR and others, have been found to be important contributors to the development and spread of cancer." (PMID 39912983, 2025). "Numerous lncRNAs, including HOTAIR, MALAT1, and PVT1, are crucial in a wide range of cancers and have significant clinical relevance." (PMID 40723840, 2025). "Genes such as FENDRR, MALAT1, FUS, and CRNDE were found to be involved in numerous cancer-stage-cell processes." (PMID 40728857, 2025). "Niclosamide, a specific inhibitor of STAT3, can negate the upregulation of MRP1 and MDR1 induced by MALAT1, highlighting the potential of targeting STAT3 to modulate drug resistance mediated by lncRNAs in cancer therapy." (PMID 41276852, 2025). "Our findings indicate that several key genes, including MALAT1 and CRNDE, are widely involved in cancer progression and exhibit various patterns in multiple cancers." (PMID 40728857, 2025).
cancer (continued). "Several key genes, including MALAT1 and CRNDE, were extensively involved in cancer progression and exhibited distinct regulate patterns across various cancers." (PMID 40728857, 2025). "Suppressing lncRNAs such as NEAT1, MALAT1, and UCA1 through various methods including CRISPR/Cas9, siRNA, or antisense oligonucleotides has been shown to impede cancer development." (PMID 39941858, 2025). "Genes MAGI2-AS3, MALAT1, and SPARC were identified as having a differential impact on the metastatic and invasive capabilities of cancer cells." (PMID 39336798, 2024). "MALAT1 was identified to interact with EZH2, the main methyltransferases of PRC2, and modulate downstream genes expression in multiple kinds of cancer cells." (PMID 39681821, 2024). "MALAT-1 modulates EMT by increasing the Slug level and enhancing cancer proliferation and metastasis." (PMID 38201661, 2024). "In multiple myeloma, MALAT-1 increases high mobility group box-1 (HMGB1) to enhance autophagy, hence inhibiting cancer cell death." (PMID 37588204, 2024). "There is also evidence that well-characterised lncRNAs such as MALAT1 and urothelial carcinoma-associated 1 (UCA1) regulate processes upstream of mTOR and that this indirect regulation of mTOR could largely be behind the involvement of these lncRNAs in cancer processes." (PMID 39062685, 2024). "MALAT1 stabilized δ‐catenin protein and upregulated HIF‐1α gene expression, both of which are master regulators of cancer glycolysis." (PMID 38639382, 2024). "For example, lncRNAs like MALAT1 and HOTAIR have been found to interact with mitochondrial components and copper transporters, thereby modulating the sensitivity of cancer cells to cuproptosis." (PMID 39325172, 2024). "This indicates that MALAT-1 regulates EMT by working as a competitive endogenous RNA and increasing NSCLC, thereby increasing cancer invasion and metastasis." (PMID 38201661, 2024). "Previous studies revealed the interplay between MALAT-1 and different microRNAs in regulating EMT and inducing cancer invasion and metastasis." (PMID 38201661, 2024). "In this review, we provide an overview of the interplay between MALAT-1 and EMT and shed light on the importance of MALAT-1 in enabling cancer invasiveness, metastasis, stemness, and chemoresistance through several mechanisms." (PMID 38201661, 2024). "Previous studies have shown that MALAT1 enhances AKAP-9 expression in CRC cells in vitro, functionally promoting cancer cell proliferation, invasion, migration, and metastatic spread." (PMID 39471147, 2024). "Echoing our observations in lung tumor tissues, both MALAT1 and MCP-1 were found to be elevated in cancer cell lines and their supernatants, relative to normal bronchial epithelial cells." (PMID 38791954, 2024). "More studies are needed to elaborate on the role of MALAT-1 in modulating CSCs and targeting MALAT-1 in different cancer types using different strategies." (PMID 38201661, 2024). "MALAT1 and SOD2 were universally expressed across all these cell types while KRT19 demonstrated higher expression in cancer and Ascending Thin Limb of Loop of Henle cells (LoH ATL cells)." (PMID 38431724, 2024). "It has been reported that miR-1-3p can be silenced by several lncRNAs such as MALAT1, DANCR, and RMRP in cancers." (PMID 39061232, 2024). "This review emphasizes the interplay between MALAT-1 and EMT in modulating cancer metastasis, stemness, and chemoresistance in different cancers." (PMID 38201661, 2024). "Some lncRNAs such as MALAT1 and HOTAIR increase the efficiency of metastatic cancer cells to develop in distal sites." (PMID 39725668, 2024). "Resveratrol inhibits the metastatic and invasion capabilities of GC mediated by MALAT-1, confirming the genuine implication of MALAT-1 in modulating EMT in different cancers." (PMID 38201661, 2024). "For instance, MALAT1 is a promising target using anti-sense oligonucleotides (ASO) in breast and lung cancers." (PMID 39598228, 2024).
cancer (continued). "MALAT-1 and NEAT1, markedly excessively expressed in various kinds of cancer, have been shown to be promoters of multiple biological processes." (PMID 38511067, 2024). "A wealth of evidence has revealed that the role of MALAT-1 is pivotal in modulating EMT, driving cells to become cancer stem cells (CSCs) or acquire stem cell–like properties, develop chemoresistance, and metastasize to distant places in the body." (PMID 38201661, 2024). "The MALAT1 ENE triplex, a specific structural motif within the MALAT1 RNA molecule, is known to play a crucial role in cancer progression and metastasis." (PMID 39015773, 2024). "Of particular interest in this context are the roles of MALAT1 and NEAT1 in regulating stem cell factors, in particular, OCT3/4 and SOX2, in LUAD and other cancer types thus having the potential to be important factors in drug tolerance." (PMID 39062685, 2024). "MALAT1, H19, and PCA3 are amongst the first lncRNAs found overexpressed in cancer, and along with many other transcripts, they were later confirmed to have important oncogenic roles." (PMID 37444543, 2023). "A few lncRNAs in this list, notably MALAT1 and NEAT1, have been studied for their regulatory roles in cancer progression." (PMID 37628839, 2023). "For example, in NSCLC, polyphyllin I inhibited the expression of MALAT1, resulting in the inactivation of STAT3 signaling pathway and apoptosis in gefitinib-resistant cancer cells." (PMID 36829256, 2023). "As part of this exercise, we confirmed MALAT1 and DANCR expression across a range of cancers and normal tissue." (PMID 36841868, 2023). "Some of the imprinted lncRNAs responsible for cancer initiation and development have been identified; these include NEAT1, MALAT1, Xist, and ZEB1-AS1." (PMID 36864364, 2023). "MALAT1, a long non-coding RNA, was found to activate AMPK signaling, promoting cancer cell proliferation." (PMID 37533434, 2023). "OIP5-AS1, TUG1, NEAT1, MALAT1, XIST, and TSIX were predicted to regulate cancer signaling in multiple tumor contexts." (PMID 38068923, 2023). "MiR-15b-5p has been reported to function as both oncogene and tumor suppressor in several human cancers, while is sponged by lncRNAs, PVT1- and MALAT1-lncRNAs among them." (PMID 37486375, 2023). "LncRNAs have been shown to be expressed in all major cancer types, contribute to the hallmarks of cancer, and can act as oncogenes (“onco-lncRNAs”, such as HOTAIR, NEAT1 and MALAT1) or tumor suppressors (e.g. GAS5, MEG3, NBAT and LINC-PINT)." (PMID 37346034, 2023). "The downregulation of MALAT1 decreases TMZ resistance by reducing the expression level of ZEB1, an EMT-related protein that increases cancer cell motility and invasiveness." (PMID 36819921, 2023). "For cancer samples, DAPK1, MLH1 and MALAT1 had higher expression, and MEG3, TIMP3 and SOX1 had lower expression when compared to normal samples." (PMID 35682732, 2022). "After targeting three important modules responsible for paclitaxel drug resistance in cancer i.e., STAT3, FUT4, and P-GP, we were interested to determine the role of MALAT1 in this scenario." (PMID 35281907, 2022). "Three well-known upstream long non-coding-RNAs (lncRNAs); MALAT1, NORAD, and NEAT1 target miR-202 and inhibit its tumor suppressive function thus fueling cancer progression." (PMID 35682549, 2022). "In our study, we also checked for the cancer stem cell markers because in our results we observed induction of EMT by MALAT1 and it is known in literature that EMT promotes cancer stem cell phenotype." (PMID 36059695, 2022). "For cancer samples, the expression level was higher than in normal samples for DAPK1, MLH1 and MALAT1, and lower for MEG3, TIMP3 and SOX1." (PMID 35682732, 2022).
cancer (continued). "The impact of si-MALAT1 and miR-20b-5p-mimic on suppression of tumorigenic abilities of HCT-116 cells has also been confirmed in xenograft model of cancer." (PMID 36582800, 2022). "Some lncRNAs act as “microRNA-sponges” to compete with mRNAs for microRNA binding, which reduce recognition rate and biological activity of microRNA consequently, while modulate the progression of cancers, such as H19, HOTAIR, MALAT1, and XIST." (PMID 35697671, 2022). "MALAT1 induces EMT and cancer stem cell phenotype and this is facilitated by sponging of miR-124 by MALAT1." (PMID 36059695, 2022). "LncRNAs, such as HOTAIR, H19, LncTCF7, LUCAT1, MALAT1, LINC00511, and FMR1-AS1, have been described as key regulators of stemness in cancer, allowing cancer cells to acquire this phenotype." (PMID 35954194, 2022). "Conversely, we show that miR-423-5p reduces MALAT-1 expression by binding to two specific regions of MALAT-1, resulting in the inhibition of its ability to promote cancer cells’ proliferation, invasion, and metastases in vitro and in vivo." (PMID 35016717, 2022). "In some cancers, the MALAT1-PI3K/Akt axis was involved in cancer metastasis, and the NF-κB pathway mediated the effect of MALAT1 on the EMT process and chemoresistance in cancer cells." (PMID 35656022, 2022). "Downregulation of LncRNA MALAT1 in both in-vivo and in-vitro model system induced the EMT process in cancer via regulation of PI3K (phosphatidylinositide-3 kinase)/Akt pathways." (PMID 36685962, 2022). "Recent studies show that various lncRNAs, such as HOTAIR, MALAT1, NRAL and TUG1, play a pivotal role in the regulation of cancer cells’ oxidative stress, highlighting a possible crossroad between lncRNAs and ROS." (PMID 36077530, 2022). "Orilnc1, KIMAT1, SLCO4A1-AS1, LINC01420, KRAS1P, YWHAE, PART1, MALAT1, PCAT-1, lncRNA-NUTF2P3-001 and TP53TG1 are long non-coding RNAs (lncRNAs) whose interactions with KRAS have been verified in the context of cancer." (PMID 35139853, 2022). "It has been reported that the lncRNA MALAT1, promotes proliferation, metastasis, and epithelial-to-mesenchymal transition (EMT) through multiple signaling pathways in several cancers, including CRC." (PMID 35814429, 2022). "Some of the lncRNA with good potential in cancer diagnosis or prognosis include PCA3, MALAT1, HOTAIR, H19, and CCAT1." (PMID 35892331, 2022). "For example, high expression of HOTAIR, MALAT1, and CCAT2 is related to poor prognosis in various cancer types." (PMID 35892331, 2022). "Such silencing of MALAT1 resulted in reversal of EMT and inhibition of cancer stem cell phenotype, along with reduced cell growth and proliferation." (PMID 36059695, 2022). "In the case of normal vs. cancer samples, significant differences were observed for the expression of MEG3, TIMP3 and MALAT1." (PMID 35682732, 2022). "Since our results above also found an inhibitory effect of MALAT1 silencing on markers of EMT and cancer stem cells, we also checked for the effect of miR-124 silencing on these markers." (PMID 36059695, 2022). "Both MALAT1 and NEAT1, significantly overexpressed in many types of cancer have been identified as regulators in several biological process." (PMID 35814429, 2022). "Further reports from recent studies showed that MALAT1 plays an important role in regulating the metastatic (LNM/distant) ability by inducing the EMT, invasion, and migration of cancer cells in OSCC." (PMID 36428681, 2022). "Similar in its mode of action to MALAT1 and NEAT1, LncRNA UCA1 upregulates cancer-promoting Sirt1, CXCR4, and activating transcription factor-2 (ATF-2) through sponging of miR-204." (PMID 35159022, 2022). "Therefore, MALAT1 may play an opposite role in cell apoptosis in different cancers." (PMID 35300579, 2022).